MIR302D (microRNA 302d)
Synonyms: hsa-mir-302d; MIRN302D; mir-302d
Gene: MicroRNA gene on chromosome 4 (112,648,004 to 112,648,071, reverse strand). Ensembl gene ENSG00000199145.
Gene Ontology:
Biological process: miRNA-mediated post-transcriptional gene silencing
Cellular component: RISC complex
Homologues: Orthologues: chimpanzee ptr-mir-302d (100% identical), macaque mml-mir-302d (97% identical), dog MIR302D (96% identical), rabbit MIR302D (91% identical), mouse Mir302d (88% identical), guinea pig MIR302D (74% identical), tropical clawed frog xtr-mir-302 (71% identical). Paralogues in human: MIR302C (81% identical), MIR302A (76% identical), MIR302B (76% identical).